SNORA17A (small nucleolar RNA, H/ACA box 17A)
Synonyms: ACA17; SNORA17
Gene: Small nucleolar RNA gene on chromosome 9 (136,726,747 to 136,726,879, reverse strand). Ensembl gene ENSG00000274998.
Gene Ontology:
Biological process: RNA processing
Cellular component: nucleolus
Homologues: Orthologues: chimpanzee SNORA17A (98% identical), mouse Gm25053 (86% identical), mouse Gm25617 (84% identical), rat Gm25617 (83% identical), guinea pig SNORA17A (83% identical), mouse Gm22149 (80% identical), mouse Gm26379 (80% identical), mouse Gm22266 (78% identical), mouse Gm23604 (78% identical), mouse Gm57326 (78% identical), mouse Gm23128 (76% identical). Paralogues in human: SNORA17B (59% identical).